ACTA2 (actin alpha 2, smooth muscle)
Diseases named in the same sentence as ACTA2 in open-access papers (continued):
Sharing a sentence is not in itself a finding about the gene and the disease.
atherosclerosis (15 papers, 2020 to 2025). A disease characterized by the build-up of fatty material and calcium deposition in the arterial wall resulting in partial or complete occlusion of the arterial lumen. "We previously determined that early-onset atherosclerosis associated with the ACTA2 p.R149C variant results from activation of SMC cytosolic stress due to misfolding of the mutant SMA monomer." (PMID 37937642, 2023). "Immunostaining in human atherosclerosis revealed abundant PAR1-expressing ACTA2+ VSMCs in human plaque fibrous caps, and PAR1 protein was also detected at lower levels in the core." (PMID 40577585, 2025). "Similar increases in Fap and Acta2 mRNA levels were observed with the progression of atherosclerosis." (PMID 40278373, 2025). "Fap appears to have a distinct expression pattern compared to other markers of activated VSMCs (Acta2 and Myh2) and proliferating or inflammatory molecules in mice models of atherosclerosis." (PMID 40278373, 2025). "Given that the proliferation and migration of VSMCs are often accompanied by cell phenotypic transformation during atherosclerosis, we also investigated the protein and mRNA expression levels of contraction phenotypic markers Acta2 and Myh11 in VSMCs." (PMID 37047626, 2023). "In contrast, myeloid-derived cells have be shown to express VSMCs markers, such as Sm22α and Acta2 in the context of atherosclerosis." (PMID 36685215, 2022). "Perhaps the most convincing evidence that EndoMT is deleterious was the correlation that both groups found between CD31+ACTA2+ cell prevalence (presumably EC undergoing EndoMT) and the severity of atherosclerosis in human atherosclerotic lesions." (PMID 36230908, 2022). "Besides, we analyzed the autophagy-related markers LC3 and smooth muscle cell marker ACTA2 located within plaques in the aortic root of the atherosclerosis model using immunofluorescence staining." (PMID 39873880, 2025). "An unannotated disease-specific cell cluster (A-cluster 6) co-expressed contractile VSMC markers (Myh11, Acta2, and Cnn1) with several atherosclerosis-induced ECM genes (Col1a1, Mgp, Eln, Fn1, Col4a1, and Col8a1) and had reduced levels of Ly6a, Vcam1, and Tnfrsf11b compared to imVSMCs." (PMID 40577585, 2025). "However, our results exhibited a lower expression of ETA-R and ETB-R as well as ACTA2 in our patient cohort, where among 69 patients with arterial hypertension, 65 had advanced atherosclerosis." (PMID 40076930, 2025). "A pathogenic variant in ACTA2, p.R149C, predisposes individuals to both thoracic aortic disease and early-onset atherosclerosis in the absence of hyperlipidemia or other risk factors." (PMID 37937642, 2023). "For ACTA2 and PCNT pathogenic variants, SMC cytosolic stress that activates HSF1/HMGCR/PERK signaling contributes to early-onset atherosclerosis, raising the possibility that SMC cytosolic stress underlies premature atherosclerosis associated with other genetic diseases." (PMID 37937642, 2023). "However, several groups using EC-lineage tracing mouse models have demonstrated that during the development of atherosclerosis, EC within the fibrous cap region undergo EndoMT and become an additional source of ACTA2+ cells." (PMID 36230908, 2022). "However, critical challenges for future studies will be to elucidate the role of different subpopulations of EndoMT EC (e.g., ACTA2+ versus ACTA2−) and identify environmental cues that regulate these EC phenotypic transitions at the different stages of atherosclerosis development." (PMID 36230908, 2022). "The accumulation of SMC_C1 (SOCS3+ ACTA2+) in the group of OCA and EC_C1 (DARC+ CD31+) in the group of atherosclerosis was further validated using pathological staining." (PMID 37706320, 2023). "Notably, both ACTA2 and fibronectin (FN1) are considered potential markers of EndoMT in atherosclerosis." (PMID 36230908, 2022).
atherosclerosis (continued). "Upregulated genes in BBA-derived VSMCs are related to arterial mineralization and atherosclerosis, such as PTX3, SPP1, LOX, etc., whereas vasodilation and physiological regulatory genes such as MGP, ACTA2, and MYL9 were conversely enriched in conventional IA-derived VSMCs." (PMID 35874788, 2022). "Nevertheless, neither of these atherosclerosis-relevant in vitro conditions were able to induce Glp1r expression, even when ECs were expressing high levels of smooth muscle markers Acta2 and Cnn1." (PMID 35401813, 2022). "Additional studies in the context of atherosclerosis reported that 30%–70% of plaque cells originate from VSMC, while up to 80% of VSMC-derived cells in the plaques do not express the VMSC markers Acta2." (PMID 36685215, 2022).
Aortic dissection (14 papers, 2014 to 2025). Aortic dissection refers to a tear in the intimal layer of the aorta causing a separation between the intima and the medial layers of the aorta. "One of the patients later died from aortic dissection — a common vascular complication of ACTA2 variants." (PMID 37587538, 2023). "Herein, we present a 21-year-old male with a familial acute aortic dissection associated with novel ACTA2 germline variant and discuss the management and surveillance considerations." (PMID 35896809, 2023). "Despite its rarity ACTA2 variants are important to diagnose as early detection can help to prevent severe vascular complications as aortic dissection, coronary artery occlusion and ischemic stroke." (PMID 37587538, 2023). "VUS of ACTA2 emerged as significantly associated with aortic dissection while COL1A1 and COL1A2 VUS significantly influenced hyperlaxity." (PMID 31536524, 2019). "The aortas of patients with ACTA2 mutations show disorganization of smooth muscle cells of the medial layer, which is consistent with the idea that medial dysfunction is the cause of aortic dissection." (PMID 29202781, 2017). "One study examined cardiovascular complications of ACTA2 in pregnancy and found a rate of 6% for third trimester or postpartum aortic dissection in a cohort of fifty three women either at risk of inheriting or diagnosed ACTA2." (PMID 29202781, 2017). "In contrast to other HTAD genes, ACTA2 mutations confer particularly low penetrance, for example, only 60% of ACTA2 R149C carriers have an aortic event (defined as repair of an aneurysm or an acute aortic dissection) by 70 years of age." (PMID 34600884, 2021). "Therefore, any patients with acute aortic dissection without systemic features suggestive of specific syndromes and with family history of aortic events should raise the suspicion for an underlying ACTA2 gene or other SMC genes." (PMID 36832261, 2023). "Identifying ACTA2 arteriopathy in patients suffering from neurological disorders and differentiating it from other cerebrovascular conditions such as cerebral atherosclerosis, vasculitis or MMA is of high relevance for the early detection of patients at risk of aortic dissection." (PMID 37587538, 2023).
coronary artery disease (14 papers, 2015 to 2024). "Studies of α-SMA and ACTA2 mutations demonstrated that it caused various vasculopathies such as the early onset of coronary artery disease, ischemic strokes, and familial thoracic aortic aneurysms and dissections." (PMID 36834717, 2023). "ACTA2 encodes the smooth muscle cell-specific actin protein and mutations in this gene have been shown to cause coronary artery disease, among other vascular diseases." (PMID 29988018, 2018). "Mutations in the ACTA2 gene trigger inappropriate proliferation of vascular smooth muscle cells leading to occlusive diseases such as coronary artery disease, stroke, Moyamoya disease and livedo reticularis." (PMID 25644172, 2015). "Studies found that mutation of ACTA2 could cause coronary artery disease and thoracic aortic disease." (PMID 35207515, 2022). "Monogenic diseases stochastically associated with MMD are often accompanied by coronary heart diseases (CHD) (BRCC3 and ACTA2)." (PMID 26662949, 2016). "One ACTA2 mutation carrier demonstrated coronary artery disease, but other features associated with ACTA2 mutations were either not present or not reported." (PMID 25644172, 2015). "Since ACTA2 R149C mutation carriers have either thoracic aortic disease or early onset coronary artery disease, the unanswered question is whether the increased retention of the mutant SM α-actin in the CCT complex conversely increases the risk for coronary artery disease." (PMID 34600884, 2021).
endometriosis (14 papers, 2020 to 2025). The growth of functional endometrial tissue in anatomic sites outside the uterine body. "Alterations in the H19/miR-216a-5p/actin alpha 2 (ACTA2) pathway may be involved in H19-mediated invasion and migration of ectopic ESCs, which could be an underlying cause of fibrogenesis or fibrosis in patients with endometriosis." (PMID 37507391, 2023). "For example, ACTA2 gene expression is increased by lncRNA H19 which sponges to miR-216a-5p to mediate stromal cell invasion and migration in endometriosis and alters stromal cell growth." (PMID 40457415, 2025). "It has been reported that H19 can stimulate the formation of fibrotic tissue in women suffering from endometriosis through the H19/miR-216a-5p/ACTA2 pathway." (PMID 38166752, 2024). "Myofibroblasts are the main source of the extracellular matrix in fibrosis, and the myofibroblast differentiation of endometriosis stroma cells includes an activation of ACTA2 expression." (PMID 38203610, 2023). "We confirmed this observation and showed that ACTA2 expression is more prominent in the endometriosis lesions of women with more advanced endometriosis." (PMID 38203610, 2023). "MYLK, ACTA2 and DMD were associated with six kinds of drugs for endometriosis, and four of which had been validated by researchers, ACACB and IGHM were associated with eight kinds of drugs, three of which had been approved by researchers." (PMID 34409913, 2021). "Another study showed that alterations in the lncRNA H19/miR-216a-5p/ACTA2 pathway affect the invasion and migration of eutopic endometrial stromal cells and contribute to fibrous tissue formation or fibrosis in women with endometriosis." (PMID 33656053, 2021). "Additionally, ACTA2, also known as alpha-smooth muscle actin (α-SMA), served as a marker for myofibroblasts associated with fibrosis in endometriosis." (PMID 40757199, 2025). "Additionally, estrogen-induced alterations in stromal cell invasion and migration in endometriosis are mediated by the H19/miR-216a-5p/ACTA2 axis." (PMID 38166752, 2024). "However, additional experimental work needs to be performed to investigate the discrete mechanism of ACTA2 regulation and the role of ACTA2 in endometriosis stromal cell adhesion." (PMID 38203610, 2023). "The estrogen-regulated lncRNA-H19/ACTA2/miR-216a-5p axis could mediate the invasion and migration of eutopic endometrial stromal cells (euESCs) in women with endometriosis." (PMID 32850438, 2020). "A shift from a pro-inflammatory milieu towards a pro-reparative environment in endometriosis lesions is accompanied by elevated expression of transforming growth factor β1 (TGF-β1) and α-smooth muscle actin (α-SMA; ACTA2), which facilitate tissue healing." (PMID 39385609, 2024). "H19 has been shown to regulate several pathways that are important in endometriosis, IGF1R, ITGB3, IER3, and ACTA2." (PMID 36232884, 2022). "ACTA2 is upregulated in ectopic lesions compared to eutopic controls in our cohort, irrespective of endometriosis disease severity." (PMID 38203610, 2023). "An increased level of ACTA2 expression within ectopic endometriosis lesions compared to endometrium tissues from women without and with endometriosis was reported." (PMID 38203610, 2023). "The positive ACTA2 stromal cells appeared to be more common in the samples isolated from the proliferative phase compared to samples isolated from the secretory stage, irrespective of endometriosis status." (PMID 35725766, 2022). "We have shown that primary ectopic stroma cells of women with endometriosis, expressing lower levels of MLLT1 and higher levels of ACTA2, compared to primary cells of women without the disease, displayed increased adhesive properties." (PMID 38203610, 2023). "Therefore, in endometriosis stroma cells, the MLLT11 regulates TGFB2 and ACTA2 expression independently, and TGFB2 signaling does not seem to be involved in the regulation of ACTA2." (PMID 38203610, 2023).
Hypertension (11 papers, 2015 to 2025). The presence of chronic increased pressure in the systemic arterial system. "KCNMB1 with ACTA2 was associated with Arterial Hypertension (q = 1.624x10-2)." (PMID 39480826, 2024). "In addition, it has been observed in heart interstitial fibrosis caused by hypertension that myofibroblasts upregulated ACTA2 expression, secrete large amounts of matrix proteins, and form a collagen-based scar." (PMID 38899223, 2024). "Altogether, our observations support a “memory” effect sustained beyond AngII-induced hypertension and leading to downregulation of specific gene expression, such as Acta2, and vascular injury." (PMID 35360022, 2022). "The annotation of DEGs in RGD (Rat Genome Database) revealed 18 genes associated with hypertension, and according to DAVID, four additional DEGs (Acta2, Hba2, P2rx4, and Sult1a1) were defined as related to regulation of BP." (PMID 32039698, 2019). "Results showed increased renal macrophage, Acta2 early in hypertension development." (PMID 41175639, 2025). "Furthermore, we observed a reduced expression of ETA-R, ET-R and ACTA2 in patients suffering from arterial hypertension, reflecting the important pathophysiologic role of the endothelin system in arterial hypertension." (PMID 40076930, 2025). "We found differences in ACTA2 in the VSMCs, suggesting that the contractile apparatus proteins may also play a direct role in the development of high blood pressure." (PMID 34755572, 2021). "Medications that reduce hemodynamic stress, such as β-blockers, should be considered in ACTA2 patients, with aortic dilatation (aortic diameter at z-score ≥ 2) or hypertension or progression of aortic dilatation (> 0,3 cm/year) and is reasonable to propose in ACTA2 patients without dilatation." (PMID 31752940, 2019). "TAGLN with ACTA2 was hypothetically associated with TRPM4/6/7/8 Signalling in Arterial Hypertension (Hypothesis) (q = 1.016x10-2), Smooth Muscle Cell Dysfunction in Arterial Hypertension (q = 1.334x10-2), and TGF-Beta Family in Epithelial Mesenchymal Transition in Cancer (q = 1.878x10-2)." (PMID 39480826, 2024). "This latter finding could be due to the hypertension-induced increase of the expression of Acta2 (significant in wt mice but not in CLR-tg mice) because the Acta2 promoter drives the transgenic overexpression of the Calclr in the CLR-tg mice." (PMID 25860809, 2015).
lung carcinoma (11 papers, 2012 to 2024). "ACTA2 is a marker for CAFs in solid tumors, and is associated with worse clinical outcome for several cancers including breast and lung cancers." (PMID 33941102, 2021). "Recent studies have shown that there is a correlation between early brain metastasis of lung cancer and the Acta2 gene mutation, and Acta2 might be a promising diagnostic and prognostic target for lung and colon cancers." (PMID 34034704, 2021). "Previous studies have shown that aberrant expression of ACTA2 promotes the invasion and migration of eutopic endometrial stromal cells and leads to significantly enhanced metastasis in lung cancer." (PMID 34858981, 2021). "Treatment with CM from 4 different lung cancer cell lines for 48 h led to increased expression of Acta2, IL-6, IL-11 and LIF." (PMID 31196220, 2019). "Moreover, researches also indicate that ACTA2 potentiates metastatic potential of human lung cancer cells via enhancing actin filament assembling." (PMID 32508931, 2020). "Furthermore, a previous study certifies that lung cancer cells with high ACTA2 expression exhibit significantly enhanced metastasis, while ACTA2 downregulation remarkably impaired metastasis." (PMID 32508931, 2020). "The same applies to another three genes KLF6 (Krüppel-like zinc finger transcription factor), MSH5 (MutS protein homolog 5) and ACTA2 (Alpha-smooth muscle actin), which were also found to be associated with lung cancer by several previous GWASs, albeit not as prominently as CHRNA5 and TERT." (PMID 27323854, 2016). "COL1A1, ACTA2, and alpha-SMA are relatively grouped in lung tissues, and PDGFRA, VCAM1 are expressed in both lung tissues and lung cancer cell lines, showing less specificity." (PMID 39034310, 2024). "In addition, knockdown of FLJ20420 expression also significantly increased the expression of PRKCBP2, TGFBR1, TGFB2, CLCN4, TRAF3, MYLK and ACTA2, while decreasing the expression of SMAD5 and prot-LBC, resulting in an increased apoptotic potential in FLJ20420-silenced lung cancer cells." (PMID 22567091, 2012). "The markers of COL1A1, COL1A2, and FAP are significantly highly expressed in lung cancer, compared to normal tissues, while PDGFRA, PDGFRB, and ACTA2 either failed to be differentially expressed in cancer tissues, or were expressed in relative lower levels." (PMID 39034310, 2024).
ovarian carcinoma (10 papers, 2016 to 2025). A malignant neoplasm originating from the surface ovarian epithelium. "More importantly, RNAscope with a sequence specific probe confirmed that the bona fide epithelial ovarian cancer cells, stained with PAX8 MAb, expressed αSMA RNA encoded by the ACTA2 gene." (PMID 35055018, 2022). "A t-SNE plot of the ovarian cancer single-cell RNA sequencing profile of the tumor microenvironment shows that COL11A1, ACTA2 (gene encoding for α-SMA), and PDPN are expressed in different, partially overlapping, ovarian CAF subsets, with COL11A1 exhibiting the most restricted expression." (PMID 36497028, 2022). "TRS3 and INOF cells differentiated into CAF-like cells when cultured with ovarian cancer cell conditioned medium as evidenced by the induced expression of the CAF markers ACTA2, FAP, collagen 1α (COL1A1), fibronectin (FN1), and fibronectin with an alternatively spliced domain A (FN-EDA) (p < 0.05)." (PMID 26716409, 2016). "C0 and C4 did not express ACTA2 or VIM, the marker genes for cancer-associated fibroblasts (CAFs), and expressed IFI6, which is associated with a malignant subpopulation in ovarian cancer, at a comparable level to other tumor clusters." (PMID 35892844, 2022). "It is also noticed that the origins of high COL1A1, COL1A2, and COL3A1 expression positively correlate with fibroblast-specific markers (FAP) and smooth muscle actin (ACTA2), whereas COL4A1, COL4A2, and COL18A1 seem to be predominantly expressed in ovarian cancer cells." (PMID 33026975, 2020). "Indeed, OGR1 was highly correlated to ACTA2 in tumors taken from CRC and melanoma patients, but not significantly correlated in breast, head and neck, or ovarian cancer patients." (PMID 29245949, 2017).